SRRM3 (serine/arginine repetitive matrix 3)
Description:
RNA splicing factor that regulates inclusion of microexons in mRNA transcripts. Required for motor coordination. In cortical neurons, acts redundantly with SRRM4 and regulates many alternative splicing events, including inclusion of exon 4 into the transcriptional repressor REST transcript, leading to REST inactivation. REST inactivation de-represses potassium-chloride cotransporter 2/SLC12A5 expression, resulting in the switch in GABAergic neurotransmission from immature excitatory to inhibitory (By similarity). Regulates inclusion of a microexon in TBC1D24 in the brain cortex (By similarity). In pancreatic islets, mediates microexon inclusion and regulates glucose- or amino acid-stimulated insulin secretion, as well as glucagon secretion. Regulates microexon inclusion in the developing retina, which is required for outer segment maintenance and vision (By similarity).
Synonyms: FLJ37078
Gene: Protein-coding gene on chromosome 7 (76,201,896 to 76,287,288, forward strand). Ensembl gene ENSG00000177679.
Subcellular location (Human Protein Atlas): Plasma membrane; Intermediate filaments; Microtubules
Genetic constraint (gnomAD): Loss-of-function variants: 26 observed, 39.05 expected, observed/expected ratio (o/e) 0.67, 90% interval 0.49 to 0.92. The synonymous counts are far from expectation, so gnomAD's model fits this gene poorly and the ratio says little. Missense variants: 866 observed, 679.43 expected, observed/expected ratio (o/e) 1.27, 90% interval 1.21 to 1.35. Synonymous variants: 365 observed, 265.06 expected, observed/expected ratio (o/e) 1.38, 90% interval 1.26 to 1.5.
Homologues: Orthologues: chimpanzee SRRM3 (99% identical), macaque SRRM3 (97% identical), dog SRRM3 (93% identical), pig SRRM3 (92% identical), rat Srrm3 (89% identical), mouse Srrm3 (89% identical), guinea pig SRRM3 (85% identical), tropical clawed frog srrm3 (54% identical).
Diseases named in the same sentence as SRRM3 in open-access papers:
SRRM3 is named in the same sentence as 8 diseases in open-access papers, as found by Europe PMC text mining. Sharing a sentence is not in itself a finding about the gene and the disease. The quoted sentences say what the papers report.
breast carcinoma (1 paper, 2025). "Luminal cells subset 2 consisted of cells expressing genes ENTPD3, SRRM3, and GPM6A (corresponding to breast cancer-related genes)." (PMID 40573402, 2025).
Cognitive impairment (1 paper, 2025). Abnormal cognition is characterized by deficits in thinking, reasoning, or remembering. "Support for a potential relevance of antibodies against SRRM3 and TSPYL5 proteins comes from the observed association between their levels and cognitive impairment, and between TSPYL5 and muscle pain, in piME/CFS patients." (PMID 41050647, 2025). "However, in the piME/CFS group, significant positive correlations were found between autoantibodies to SRRM3 protein and cognitive impairment, and between antibodies to TSPYL5 protein and both cognition and muscle pain." (PMID 41050647, 2025).
multiple sclerosis (1 paper, 2025). A progressive autoimmune disorder affecting the central nervous system resulting in demyelination. "In multiple sclerosis, autoantibodies to SRRM3 have been detected years before the disease onset." (PMID 41050647, 2025).
periodontitis (1 paper, 2022). An acute or chronic inflammatory process that affects the tissues that surround and support the teeth. "Furthermore, 12 hub genes ranked by the top 10% genes with high degree connectivity and five TFs, including SRF, CNOT4, SIX6, SRRM3, NELFA, and ONECUT3, were identified and might play crucial roles in the molecular pathogenesis of periodontitis." (PMID 35397550, 2022).
cancer (1 paper, 2015). A tumor composed of atypical neoplastic, often pleomorphic cells that invade other tissues. "Our results reveal regulatory interactions among REST, REST-003, and a cancer cell-specific splicing activator (SRRM3) that may coordinate gene regulation required for development of the invasive cancer phenotype in breast cancer." (PMID 26053433, 2015).
tumor (1 paper, 2021). "Interestingly, our results suggest that SRRM3 is not involved, despite being thought to regulate similar targets as SRRM4, as its expression is increased in a majority of tumor types." (PMID 33621242, 2021).
SRRM3 also shares sentences with these, for which no sentence is quoted: Anxiety (1 paper); sarcoidosis (1).